TYR (tyrosinase)
Diseases named in the same sentence as TYR in open-access papers (continued):
Sharing a sentence is not in itself a finding about the gene and the disease.
melanoma (continued). "Dehydroglyasperin C, a major prenylflavonoid of Glycyrrhiza uralensis (Fabaceae), suppressed intracellular tyrosinase activity and related proteins (TYR-1 and TRP-2) at a low concentration (1 μM) in α-MSH-induced B16F1 melanoma cells." (PMID 34946631, 2021). "In daily practice, the conventional pan-melanoma cocktail (HMB-45, melan-A, and tyrosinase), along with S100 can be successfully used for the identification of the melanocytic origin of tumor cells." (PMID 33801642, 2021). "Next, mRNA encoding the fusion of an MHC class II protein (DC-LAMP) with four melanoma antigens (Gp-100, MAGE-A3, tyrosinase, and MAGE-C2) is delivered." (PMID 34885078, 2021). "The rate of positivity for the conventional-adapted pan-melanoma cocktail (triple positivity for HMB-45, tyrosinase, and SOX10) was 38.63% (n = 17)." (PMID 33801642, 2021). "Both MUG Mel3 NPF and MUG Mel3 NPh highly expressed each of the stained melanoma markers HMB45, Melan-A, Tyrosinase, and MCSP." (PMID 34768746, 2021). "Quercetin treatment of cultured melanoma cells or NHEM promote melanin synthesis and tyrosinase activity." (PMID 34858164, 2021). "In human melanoma cells (HMV-II), the expression of tyrosinase and MITF was reduced after treatment with citric acid, aligning with the intracellular melanin content of HMV-II cells." (PMID 33332393, 2020). "The inhibition of BRAF and MEK leads to up-regulation of melanoma differentiation antigens (MDA), such as MART-1, gp-100 and tyrosinase, and MHC expression along with decreased immunosuppressive cytokines secretion." (PMID 32054102, 2020). "S-100 is a highly sensitive marker for melanoma; HBM-45, melan-A, MITF and tyrosinase are highly specific markers for this entity." (PMID 32724562, 2020). "As to the mechanism of inhibition of melanogenesis, FUBRS potently decreased cellular tyrosinase activity in a dose-dependent manner, consistent with the dramatically decreased cellular melanin content in B16F10 melanoma cells." (PMID 32423183, 2020). "Among other X-linked miRNAs, miR-374, part of the human miR-374 family, down-regulates tyrosinase expression and reduces melanoma malignancy by attenuation of WNT signaling, thus promoting melanoma cell apoptosis in a mouse model of melanoma." (PMID 32645881, 2020). "Results showed that non-cytotoxic doses of LSE and its main component epigallocatechin (EGC) reduced both tyrosinase activity and melanin production in the α-MSH-induced melanoma cells." (PMID 33218008, 2020). "In the present study, we determined the anti-melanogenesis and tyrosinase inhibitory activities of IPA, a phlorotannin isolated from IO and IOE, in a vertebrate model of zebrafish in vivo and in B16F10 melanoma cells in vitro, after induction with α-MSH." (PMID 32957728, 2020). "In B16F10 murine melanoma cells stimulated with the melanocyte hormone α-MSH, AL inhibited phosphorylation of PKA and CREB and downregulated protein expression of tyrosinase and MITF." (PMID 32120828, 2020). "We also found that the tyrosinase activity and melanin content were inhibited by PH treatment in B16F10 melanoma and normal human melanocytes cells." (PMID 32630811, 2020). "B16F10 melanoma cells were treated with varying concentrations [1, 2.5, and 5% (v/v)] of FUBRS and then the cellular tyrosinase activity was measured." (PMID 32423183, 2020). "It is also known that bioactivation of CAPE to its corresponding quinone metabolite by tyrosinase would lead to GST inhibition and selective melanoma cell death." (PMID 32456290, 2020). "Using the human melanoma cells SK-MEL-1 as a model, an increase in both tyrosinase activity and melanin was already observed at 24 h after melatonin treatment with maximal levels of both being detected at 72 h." (PMID 32674468, 2020).
melanoma (continued). "However, compared to combined controls (3.13% BNMS/2.04% MGRB), there was a highly significant greater occurrence of TYR+OCA2 deleterious alleles in total melanoma cases (SMMAT P = 0.008), but not AHM (SMMAT P = 0.90), nor in comparison between AHM and PM (SMMAT P = 0.095)." (PMID 32966289, 2020). "Since TYR and TYRP1 are MITF target genes, we interrogated previously published ChIP-seq datasets to determine if BRD4 and MITF co-occupy MITF-binding sites at the TYR and TYRP1 loci in melanocytes and melanoma cells." (PMID 32151278, 2020). "In this study, a combination of Al and Gg extracts was investigated for cellular tyrosinase inhibitory activity, reduction of melanin contents and downregulated expression of melanogenesis-related genes MITF, TYR, TRP-1 and TRP-2 in melanoma B16 cells." (PMID 33066628, 2020). "The genes for markers melanogenesis tyrosinase (TYR) and transcription factor MiTF (MITF), which are specific for melanoma cells, were observed predominantly in the pool of melanoma cells." (PMID 33182777, 2020). "The FUBRS likely reduced melanogenesis by inhibiting tyrosinase activity and the expression levels of tyrosinase, TYRP1, and TYRP2 via inhibiting expression of MITF in B16F10 melanoma cells." (PMID 32423183, 2020). "We analyzed expression of 3 melanoma antigens, gp100 (HMB-45), Melan-A (MART1) and Tyrosinase in skin biopsy samples from metastatic melanoma patients." (PMID 32231230, 2020). "Additional tumor-associated antigen (TAAs) derived HLA ligands are frequently identified by MS, such as “normal” (wild-type) proteins overexpressed or restricted to tumors (e.g., MelanA, Tyrosinase, PMEL in melanoma; NY-ESO in multiple cancer types)." (PMID 31440238, 2019). "This specificity of ANRU TIL for MART-1 and weakly for gp100 was confirmed by FACS analysis using a panel of dextramers for common melanoma antigens (MART-1, NY-ESO-1, MAGE-A3, Tyrosinase, gp100, and MAGE-A1)." (PMID 31921104, 2019). "Dacryocystectomyrevealed diffuse infiltration with large epithelioid cells, sometimes withpigments, which were positive for cocktail mix of antibodies to tyrosinase,melan A (MART-1), and HMB45, leading to pathological diagnosis of melanoma." (PMID 31747798, 2019). "Tyrosinase is involved in the synthesis of melanin, MAGE-3 is involved in malignant transformation and is the main tumour-specific melanoma antigen, and MCAM is involved in cell adhesion." (PMID 31572192, 2019). "It was found that the level of tumor tyrosinase in mice treated with CMSP increased, while the levels of melanoma markers S-100B, MIA-A, and MMP-9 decreased." (PMID 31683690, 2019). "In successive experiments BID3 cellular tyrosinase potential and melanin production in α-MSH and IBMX-induced B16F10 melanoma cells was also explored." (PMID 31921392, 2019). "We found that SA-4 cells also express several genes typical of melanomas, such as MITF, MLANA, S100B, and TYR, which are otherwise poorly expressed in our panel of liposarcoma cell lines." (PMID 29570692, 2018). "36H was also measured for tyrosinase inhibitory activity applying various species platforms, including in vitro mushroom, B16F10 mouse melanoma, and human melanocyte cells." (PMID 29507652, 2018). "The results indicated that sesamol inhibited tyrosinase activity and melanogenesis induced by α-melanocyte-stimulating hormone (α-MSH) in B16F10 melanoma cells." (PMID 29642438, 2018). "In summary, compound 3 decreased melanin production and intracellular tyrosinase activity by modulating CREB and p38 signaling pathways in α-MSH-activated B16-F10 melanoma cells." (PMID 30297610, 2018). "In this study, we characterize and evaluate of 1c of its tyrosinase inhibitory activity and the modulatory role in melanin synthesis using B16F10 murine melanoma cells." (PMID 30360412, 2018).
melanoma (continued). "The results of western bolt assay showed thatECPS suppressed the expression of TRP-1, tyrosinase, and MITF in B16F10 cells andimplied that ECPS decreased melanogenesis by down-regulating tyrosinase, MITF, andTRP-1 expression in B16F10 melanoma cells." (PMID 29846408, 2018). "The assays was performed by using a mushroom tyrosinase enzyme and melanin contents on α-MSH and IBMX-induced B16F10 melanoma cells." (PMID 30360412, 2018). "Ascorbic acid stimulates melanogenesis in B16F10 murine melanoma cells by expression of MITF, tyrosinase, TRP-1, and TRP-2, as well as activation of the MAPK family, accelerates p38 activation and suppresses activation of JNK and ERK." (PMID 29019940, 2017). "mRNAs encoding a single antigen (CEA in the case ofcolorectal cancer) or a combinationof antigens (MAGE-A1,-A3,-C2, tyrosinase, MelanA/MART-1, and gp100 for melanoma) were also used to load DCs." (PMID 29104773, 2017). "The phosphorylation and activation of p38 MAPK in B16 melanoma cells was found to increase melanin synthesis through increased expression of MITF and TYR via CREB phosphorylation." (PMID 28946635, 2017). "The 10-HDA dramatically inhibited tyrosinase, TRP-1 and TRP-2 expressions in B16F1 melanoma cells compared with those of the untreated cells." (PMID 28793915, 2017). "FPE reduced melanin content, inhibited activity of TYR, and increased GSG/GSSG in B16 melanoma cells." (PMID 28337140, 2017). "Transcripts of MLANA, TYR, MAGEA3, PAX3, and ABCB5 were successfully identified from a single melanoma cell, as reflected by the increase in reciprocal Ct values (1/Ct)." (PMID 28978038, 2017). "Among the five most potent extracts, the methanol extract of Morus alba wood (MAM) demonstrated a significant reduction in intracellular tyrosinase and melanin content in B16F10 melanoma cells." (PMID 28333105, 2017). "In this study, we assesses the 10-HDA whitening activity in comparison with the changes in the intracellular tyrosinase activity, melanin content and melanin production related protein levles in B16F1 melanoma cells after treating with 10-HDA." (PMID 28793915, 2017). "Western blotting demonstrated that SASH1 mutations significantly increased TYRP1, Rab 27a, Pmel17 and tyrosinase protein levels in SK‐MEL‐28 cells, a pigmented melanoma cell line and NHEMs." (PMID 27885802, 2017). "All together, these results indicate that, in melanotic melanoma cells, miR-211 is induced by BRAFi/MEKi and favors their pro-pigmentation activity by targeting EDEM1, hence promoting TYR expression and melanin accumulation." (PMID 28445987, 2017). "The methanol extract of Morus alba wood demonstrated the highest tyrosinase inhibition among the 900 extracts tested, as well as a significant reduction in intracellular tyrosinase and melanin content in B16F10 melanoma cells." (PMID 28333105, 2017). "10-HDA inhibited not only the tyrosinase activity, but also the melanogenic enzyme expressions, including tyrosinase, TRP-1 and TRP-2, by suppressing MITF in the B16F10 melanoma cells." (PMID 28793915, 2017). "For example, promoters of melanoma biomarkers such as Cox-2, CXCR-4, tyrosinase and survivin have been incorporated into the viral genomes, which result in significantly enhanced oncospecificity." (PMID 28567163, 2017). "In WM35 melanoma, the tyrosinase protein level was increased by GaPc-PDT compared to controls, while Metformin and GaPc-PDT decreased tyrosinase, compared to controls." (PMID 28278159, 2017). "When melanoma cells with high MITF levels were transfected with a vector for expression of OCT4 there was a reduction of both TRPM1 and TYR expression." (PMID 29044103, 2017). "Previously, the influence of aromatic-turmerone on inhibiting melanogenesis was suppressed by CREB activation, and expression of MITF, tyrosinase, TRP-1, and TRP-2 in B16F10 melanoma cells." (PMID 29019940, 2017).
melanoma (continued). "The FEE showed the best scavenging capacity and mushroom tyrosinase inhibitory activity, so its ability to affect the viability of B16F10 melanoma cells was also evaluated." (PMID 27829416, 2016). "The aim of this study was to investigate the inhibitory activity of three different extracts of A. microcarpus on tyrosinase activity and on melanogenesis in B16F10 melanoma cells." (PMID 27829416, 2016). "The upregulation of MITF correlated with increased expression of its target genes TYR and MLANA, which is in line with previous observations of increased melanoma differentiation antigen expression on treatment, and indicates that MITF is functional." (PMID 26977879, 2016). "Molecular evidences suggested that melanin synthesis was inhibited via the down-regulation of tyrosinase, tyrosinase-related protein (TRP)-1, and TRP-2 expression in B16F10 melanoma cells treated with LASAP-C." (PMID 27424198, 2016). "Melanoma cells express melanoma-specific antigens, such as the well-characterized melanoma differentiation antigens MelanA (MART-1), gp100 (pmel) and tyrosinase that can be recognized by CTLs via their T cell receptors (TCRs)." (PMID 27625650, 2016). "Anti-melanogenic efficacy was evaluated by tyrosinase, tyrosinase-related protein (TRP)-1, and TRP-2 expression in B16F10 melanoma cells." (PMID 27424198, 2016). "In the case of melanoma, specific melanoma antigens are incorporated (MART1/Melan-A, gp100, tyrosinase), which should be potentially recognized by cytotoxic T lymphocytes." (PMID 27998306, 2016). "Tyrosinase activity and melanin content in murine B16F10 melanoma cells were increased by cirsimaritin in a dose-dependent manner." (PMID 25903150, 2015). "In melanoma cells, MITF-M regulates the expression of differentiation genes like TYR (tyrosinase), MLANA (Melan-A/Mart-1) or SILV (pMel17/gp100)." (PMID 25853464, 2015). "As PD-L1 can also be expressed on melanoma cells, we used a cocktail consisting of HMB45, Mart-1 and Tyrosinase to identify tumor cells." (PMID 26500776, 2015). "The results revealed that E. camaldulensis flower essential oil effectively suppresses intracellular tyrosinase activity and decreases melanin amount in B16F10 mouse melanoma cells." (PMID 25961954, 2015). "Melanoma cells express various antigens including gp100, melanoma antigen recognized by T cells 1 (MART-1), and tyrosinase, which can induce immune-mediated anticancer response via T cell activation." (PMID 25918658, 2015). "IC50 of mimosine dipeptides against intracellular tyrosinase and melanin content in B16F10 melanoma cells." (PMID 26287130, 2015). "The ability of E. characias extracts to inhibit tyrosinase activity was evaluate using cell-free mushroom tyrosinase and a cellular system with B16F10 mouse melanoma cells." (PMID 26500815, 2015). "Source proteins for melanoma epitopes included tyrosinase, MART-1, gp100, and MAGE-A3, all known to be expressed by Melanoma GVAX." (PMID 26143264, 2015). "Tyrosinase activity in GAE-treated and cultured B16F10 melanoma cells was suppressed in a dose-dependent pattern." (PMID 26702819, 2015). "Twenty compounds including eight benzofurans, 10 flavonoids, one stilbenoid and one chalcone were isolated from M. alba leaves and these phenolic constituents were shown to significantly inhibit tyrosinase activity and melanin content in B6F10 melanoma cells." (PMID 26007176, 2015). "M. alba leaves exert anti-melanogenesis inhibitory activity as measured by tyrosinase inhibition and melanin content in B16F10 melanoma cells." (PMID 26007176, 2015). "Among these genes, the transcription factor MITF, the pigmentation enzyme TYR, and MLANA and GPR143 that are involved in melanosome biogenesis, are important players in melanoma." (PMID 25207815, 2014). "Subsequently, the pro-drug TMECG was activated by tyrosinase and consequently inhibited dihydrofolate reductase (DHFR) leading to apoptosis of melanoma cells." (PMID 25538895, 2014).
melanoma (continued). "qRT-PCR analysis showed expression of melanoma differentiation markers MLANA, TYR and MITF in the panel of 54 melanoma cell lines." (PMID 25051363, 2014). "AM-EO can suppress the production of melanin by downregulation of tyrosinase activity through the regulation of the JNK and ERK signaling pathways in α-MSH treated melanoma cells." (PMID 24743745, 2014). "A histological melanoma is confirmed by the Fontana-Masson silver stain and the appropriate immunohistochemical staining pattern that includes HMB-45 antibodies, Melan-A, tyrosinase, and antimicrophthalmia transcription factor." (PMID 25642350, 2014). "Analysis of mRNA expression levels of CD271, CD133, ABCB5, SOX2 and melanoma markers SOX10, NES and TYR, MART-1 and MITF-M revealed a strong heterogeneity among the PM tissue samples." (PMID 24799129, 2014). "We therefore examined the expression of melanoma-specific differentiation genes including Melan-A (MLANA), Tyrosinase (TYR) and Tyrosinase-related protein 1 (TYRP1) by quantitative PCR." (PMID 24406338, 2014). "It was also reported to decrease tyrosinase activity and melanin biosynthesis in B16F10 melanoma cells." (PMID 28510887, 2013). "TRP1, as well as tyrosinase, TRP2, and gp100, are melanocyte differentiation antigens that are clinically relevant antigens in both autoimmune vitiligo and melanoma." (PMID 24409178, 2013). "In melanoma cell lines, MEK and BRAF inhibition leads to increased expression of melanoma differentiation antigens (MDAs) such as gp100, MART-1, and tyrosinase on the mRNA and protein levels." (PMID 24194739, 2013). "It inhibits melanin synthesis in murine B16F10 melanoma cells, by reducing MITF and inhibiting the tyrosinase activity." (PMID 23431351, 2013). "Together with gp 100, and for the case of melanoma, two more tumor genes have been described for DNA vaccination: MART-1 and tyrosinase." (PMID 23634303, 2013). "Sixteen melanoma patients were treated using autologous monocyte-derived DC pulsed with a cocktail of gp100, MART-1, tyrosinase, MAGE-1, or MAGE-3 peptides chosen to suit the individual patient’s class I HLA molecules." (PMID 24379816, 2013). "MU melanoma cells exposed to T-oligo express MART-1 after 24 hrs with additional expression of TRP-1, tyrosinase and TRP-2 after 96 hrs." (PMID 23800953, 2013). "In contrast, healthy controls had uniformly higher levels of TYR and MITF than melanoma patients (p<0.0001)." (PMID 22829910, 2012). "In contrast, transcript levels were significantly higher for TYR and MITF (each p<0.0001) in blood from healthy control subjects vs. melanoma patients, again both in blood samples drawn at the time of surgery as well as those drawn one week following surgery." (PMID 22829910, 2012). "We have reported previously that daily intravenous infusions of a soluble nanobiotechnological complex, polyhemoglobin-tyrosinase [polyHb-Tyr], can suppress the growth of murine B16F10 melanoma in a mouse model." (PMID 23209910, 2012). "Previously, we have reported that daily intravenous infusions of a soluble nanobiotechnological complex, polyhemoglobin-tyrosinase [polyHb-Tyr], can suppress the growth of a murine B16F10 melanoma in a mouse model." (PMID 23209910, 2012). "It has been shown that in the melanoma cells stimulated with 0.3% and 1% DMSO, the increase of transcriptional activity of the tyrosinase gene took place." (PMID 22654640, 2012). "Furthermore, we targeted tumour initiating CMCs that do not always express common melanoma associated antigens so confirmation by positive staining of markers such as MART-1 or tyrosinase could result in exclusion of these cells." (PMID 22978632, 2012). "The inhibitory effect of the essential oil on melanogenesis was evaluated by a mushroom tyrosinase activity assay and B16F10 melanoma cell model." (PMID 23203088, 2012). "A375 is also a HLA-A*0201-positive melanoma line but is defective in intracellular processing and MHC presentation of gp100, MART-1, and tyrosinase." (PMID 21794122, 2011).